PAX8 (paired box 8)
Diseases named in the same sentence as PAX8 in open-access papers (continued):
Sharing a sentence is not in itself a finding about the gene and the disease.
cancer (continued). "SurePathTM technology, using 3D cluster patterns and dual ICC for CK7 and PAX8 in peritoneal fluid samples, can provide important information for determining specific primary origins in cases of unknown primary carcinoma." (PMID 30024911, 2018). "It was found that BRAF V600E, RET/PTC1 and TERT mutations were associated with aggressive characteristics, whereas BRAF K601E, HRAS, NRAS, KRAS, PAX8-PPARy mutations and tumors with no mutations are significantly less likely to be associated with high risk cancers." (PMID 33910629, 2021). "Further investigation into the functional relationships of RAG2 and PAX8 with cancer associated genes, especially those that are not typically expressed in the thyroid, is needed to fully understand and potentially disrupt these disease pathways using innovative therapeutic interventions." (PMID 33716974, 2021). "However, the expression of PAX-8 among the studied samples was relatively low compared to previous studies, this could be attributed to the site of cancer development." (PMID 32847623, 2020). "In differentiated thyroid cancers, several genetic alterations such as BRAFV600E mutation, RET/PTC or PAX8/PPARγ translocation and RAS mutation are thought involved in carcinogenesis in thyroid follicular cells, and further genetic change drives stepwise dedifferentiation of cancer cells." (PMID 31666923, 2019). "Therefore, we speculate that PAX8-mediated signaling pathways are unique to specific cancer cell types." (PMID 30021604, 2018). "Functionally, IGF2BP2 promotes proliferation, suppresses thyroid differentiation genes (TSHR, SLC26A4, SLC5A5, TPO, PAX8, FOXE1, and NKX2.1), and enhances cancer stemness." (PMID 41522349, 2026). "MethSig cancer genes were also enriched in developmental genes (for example, PAX6, PAX8 and TBX4), suggesting a potential role for DNA methylation in cell plasticity." (PMID 40931149, 2025). "The epithelial OC origin of the PDC2 and PDC3 samples was confirmed by the expression of OC-specific markers PAX8 and CD24, epithelial makers MKI67, EPCAM, KRT8 and KRT18 and cancer stem cell markers such as CD44 and ROR1." (PMID 39482470, 2025). "Excisional biopsy confirmed poorly differentiated carcinoma; immunohistochemistry (IHC) was positive for PanCK, CK7, TRPS1, and PAX8 with a high Ki-67 index (70%)." (PMID 40656412, 2025). "A liver biopsy confirmed a PAX-8 and CD10 positive carcinoma, consistent with metastatic renal cell carcinoma." (PMID 40370715, 2025). "PAX8 and CK7 expression was partially or completely lost (while being retained in the conventional carcinoma component, when present)." (PMID 39408649, 2024). "Specifically, the molecules involved in cancer-related pathways, including LAMB3, KEAP1, Bid, EGFR, Bcl-XL, Bcl-2, and PAX8, were all regulated by JorA." (PMID 37587470, 2023). "Similar to the role of PAX8 in renal development and ccRCC, IRF2 plays an important role in cancers originating from the plasma cell lineage." (PMID 37554444, 2023). "To validate the RNA-seq analysis, we selected seven representative genes on the basis of their relevance for HGSOC (PAX8, EGFR) and other cancers (GATA6, RBM47, KHDRBS3), or for their involvement in the DDR pathway (ATRIP, POLH)." (PMID 37202753, 2023). "Nonetheless, evidence shows that the knockdown of PAX8 in HGSOC results in increased apoptosis and reduced proliferation and migration in cancer cell lines." (PMID 33121525, 2020).
cancer (continued). "For example, ASCL1, CDX2, IRF4, MITF, NKX2-1, PAX8 and SOX2 were pinpointed as outliers in cell lines of their corresponding cancer tissue origins." (PMID 31050342, 2019). "Data showed that PAX8 silencing abolished the effect of LDR on NIS and TG upregulation in 850-5C cancer cells." (PMID 30760304, 2019). "While the CRC mapper output consisted of multiple TFs, intersection with transcriptomic and functional genomic datasets highlighted the importance of PAX8 and HNF1B in cancer cells proliferation." (PMID 31431624, 2019). "Also, the direct regulation of PAX8 is not only important in controlling the protein levels of ITGB3 but also in turn affects the αvβ3 heterodimer expression on the plasma membrane which could alter the cancer cell migratory properties." (PMID 31832016, 2019). "For TF AREB6, expression was found only in one malignant sample, while for PAX8 and ELF3 the expression pattern was present in normal and cancer samples." (PMID 20181230, 2010). "This is the first report of methylation in any cancer for five loci (CPVL, HOXC9, PAX8, PTPRN2, and SLC38A4), flagging these loci as potential novel cancer markers." (PMID 18616821, 2008). "This was corrected through IHC testing, which confirmed the mesothelial cell lineage (calreticulin-positive, WT-1-positive, D2-40-positive) and excluded cancer markers (e.g., PAX-8-negative)." (PMID 41395612, 2025). "Immunohistochemistry results with intestinal CDX-2 staining were as follows: cancer cells CDX-2 (+), Pax-8 (-), uterine and bilateral adnexa, high-grade adenocarcinoma (originating from the female reproductive system) with extensive necrosis in the right ovary, and 0.1-cm thick cancerous residue." (PMID 41127008, 2025). "Indeed, the downregulation of the paired box 8 (PAX8) and peroxisome proliferator-activated receptor gamma (PPARG) genes in PTC tissues leads to the metastasis of cancer cells to lymph nodes and distant tissues." (PMID 36523971, 2022). "When evaluated for mutation, 77.7% of cancers had BRAF V600E; 8.8% showed RET/PTC rearrangements; 4.4% were positive for PAX8/PPAr gamma and 9.1% had RAS mutations (H- and K-, no NRAS mutations were found in our series)." (PMID 34350538, 2022). "We performed immunostaining for transcription factor E3 (TFE3), human melanoma black 45 (HMB45), melan-A, desmin, pan-cytokeratin (CK), paired box 8 (PAX8), CD10, hormone receptors, and S100, and targeted RNA and DNA sequencing using commercially available cancer gene panel." (PMID 35626258, 2022). "We hypothesize that this compound will have similar effects in other cancer cell types which also aberrantly express PAX proteins at a high level, particularly PAX2, and potentially PAX5, PAX6 or PAX8." (PMID 34722257, 2021). "Mesothelial cells are generally positive for calretinin, thrombomodulin, cytokeratin 5/6, WT1, D2-40, vimentin, HBME-1 and CD44H, while polyclonal and monoclonal carcinoembryonic antigen, Ber-EP4, Leu-M1, CA-125, B72.3, PAX8, MOC 31, CA19-9 and ER are the most common markers of carcinoma." (PMID 34068638, 2021). "Here, we report that RNAi silencing of PAX8 sensitizes non-adherent cancer cells to anoikis and affects their tumorigenic properties." (PMID 31832016, 2019). "Outside BRAFV600E, the likelihood of cancer for those variants documented as positive in at least 10 nodules in the included studies (BRAFK601E, HRASq61R, NRASq61R, and PAX8/PPARG fusion) ranged from 37% to 55%." (PMID 31469053, 2019). "Finally, we discovered eight genes (MME, SOX17, AGTR1, PGR, ESR1, PAX8, C3 and IRF6) with high amplification frequency compared to other genes across the cancer types." (PMID 31879572, 2019).
cancer (continued). "The 76 cases showing morphologic features consistent with cancers of ovarian primary were all positive for PAX8 and negative for Calretinin." (PMID 23958394, 2013). "Although these cancer cell lines also express TSHR and the thyroid transcription factor Pax8, other markers of terminally differentiated thyroid cells, such as the sodium-iodide symporter and thyroglobulin, are not expressed in these cell lines (Friedman and Lin, unpublished observations)." (PMID 19404394, 2009). "Immunohistochemistry has been performed and revealed that the carcinoma was strongly and diffusely positive for cytokeratin 7 (CK7), GATA-binding protein 3 (GATA3), and p40, and was negative for oestrogen receptor (ER), progesterone receptor (PR), and paired box gene 8 (PAX8)." (PMID 40656261, 2025). "Moreover, the cancer cell growth could be restricted, even in the ADSC‐treated group (P < .05), by inhibiting PAX8." (PMID 33830648, 2021). "However, it should be noted that such a disease is difficult to diagnose based only on the expression of PAX-8, and it is important to rule out other cancer types by histological examination or image-based findings." (PMID 32748087, 2020). "Also, HOPX was correlated with genes in a manner toward suppression of cancer cell progression; downregulation of TNRC6C, PAX8, TSHR, DYRK1A/B, and SLIT3 (pro-proliferation/migration), and upregulation of PCDH8/9, CDC42EP3/4/5, and TJP3 (anti-proliferation/migration)." (PMID 31666923, 2019). "PTH, GCM2, SYN, CgA, GATA3, and CAM5.2 are always positive in cancer cells, while TTF1, PAX8, CAL, and TG are always negative." (PMID 38019325, 2023). "Epithelial carcinomas were also excluded based on the negative results for EMA (Epithelial membrane antigen) and PAX8." (PMID 35797874, 2022). "Immunohistochemical analyses of the cancer cell line (passage number 23) also showed ALK expression (ALK-positive) and confirmed thyroidal origin (TTF1 positive, PAX8 positive, thyroglobulin negative)." (PMID 33878728, 2021). "In immunohistochemistry, the cancer cells were immunoreactive for WT1, PAX8, and CA125, and negative for GATA3, mammaglobin, and gross cystic disease fluid protein-15." (PMID 33593410, 2021). "In immunohistochemistry, the cancer cells were immunoreactive for WT1, PAX8, and CA125, and negative for GATA3, mammaglobin, and gross cystic disease fluid protein-15 (GCDFP15)." (PMID 33593410, 2021). "In spite of various histologic subtypes by an adequate biopsy and positive PAX8 immunohistochemical staining, ATC is almost indistinguishable from any other poorly differentiated carcinoma." (PMID 32336952, 2020). "This disparity may be due to the higher percentage of cancer documented in American RAS-mutated indeterminate nodules, possibly because the Bethesda and SIAPEC classifications do not perfectly overlap, and/or because our panel did not include RET/PTC and PAX8/PPARG rearrangement analysis." (PMID 29085338, 2017). "Further differentiating them from renal epithelial tumors, melanotic Xp11 cancers are unique in their lack of reactivity with PAX-2 and PAX-8." (PMID 24735727, 2014). "A detailed battery of immunohistochemical (IHC) studies supported the diagnosis and showed expression of the pancytokeratin (CKAE1/3), CK7, PAX8 and the epithelial membrane antigen (EMA) markers in the carcinoma component, with no immunoreactivity in the sarcoma (osseous) component." (PMID 40027125, 2025).
cancer (continued). "Staining for p40 and p63 was positive in only a few cells (nonspecific staining), and staining for CD10, PAX-8, and CK20 was negative, supporting the exclusion of other possible primary carcinomas, including squamous cell carcinoma and carcinoma of Müllerian origin." (PMID 39022491, 2024). "Immunohistochemistry (IHC) was nonspecific and inconsistent (positive for pancytokeratin, PAX8, and CDX2, and negative for CK7, CK20, ER, WT1, calretinin, CD31, CD34, and synaptophysin) and working diagnosis was a putative upper gastrointestinal versus mullerian cancer profile." (PMID 27171493, 2016).
adenocarcinoma (27 papers, 2014 to 2025). A common cancer characterized by the presence of malignant glandular cells. "Cytology from her thoracentesis revealed PAX8-positive adenocarcinoma indicative of a gynecologic origin." (PMID 34200645, 2021). "Thoracentesis studies revealed an exudative pleural effusion positive for malignant cells showing adenocarcinoma, which had an immunopathologic profile (WT-1 and PAX8) favoring an adenocarcinoma of kidney origin." (PMID 33815993, 2021). "PAX8 is positive in 68% to 80% of gastric-type adenocarcinomas, which is useful in distinguishing these tumors from adenocarcinomas of gastrointestinal or pancreatobiliary origin." (PMID 33570865, 2021). "There were only 14 patients who had positive expression of PAX-8; including 11/15 (73.3%) adenocarcinoma and 3/45 (6.7%) SCC." (PMID 32847623, 2020). "All LAMN cases exhibited a similar immunoprofile (CK20+, CDX2+, PAX8−), while the adenocarcinoma case co-expressed CDX2 and SATB2 with negativity for CK7, CK20 and PAX8." (PMID 31771640, 2019). "The tumors had a histology of poorly differentiated adenocarcinoma, expressing human epithelial pancytokeratin (CK) and PAX8." (PMID 28977852, 2017). "Several entities were considered in the differential diagnosis, including mesonephric-like adenocarcinoma; however, the absence of characteristic morphologic features and the lack of PAX8 and GATA3 expression did not support this diagnosis." (PMID 41517393, 2025). "PAX8 is positive in this type of adenocarcinoma, whereas it is negative in conventional adenocarcinoma." (PMID 37233807, 2023). "Bronchoscopy with biopsy confirmed metastatic lung adenocarcinoma, with histopathology showing moderately differentiated adenocarcinoma, positive for TTF-1 and Napsin A and negative for PAX8." (PMID 40708867, 2025). "The immunohistochemistry (IHC) profile of positive CDX2 and CK20 and negative PAX8, CK7, ER, and PR suggested a colorectal-type somatic adenocarcinoma arising from the MCT and was staged as IA, after negative endoscopic findings." (PMID 37753035, 2023).
gynecologic tumors (5 papers, 2018 to 2026). "Our study demonstrated that PAX2 and PAX8 were more upregulated in MLAs than in conventional gynecologic tumors and were enriched in mesonephric tubule morphogenesis." (PMID 40740763, 2025). "Tumors, if observed, were additionally stained with paired-box transcription factor PAX8, a biomarker used to help define gynecologic tumors in humans, but is also expressed in embryogenesis of the thyroid, renal, and upper urinary tracts." (PMID 38352443, 2024). "Immunohistochemistry was positive for PAX8 and cytokeratin-7, suggesting a gynecological origin, although no primary gynecological tumor was identified on imaging." (PMID 41684973, 2026).
infection (3 papers, 2017 to 2021). The state of being infected such as from the introduction of a foreign agent such as serum, vaccine, antigenic substance or organism. "The specific expression levels of Pax2, Pax8, Eya1, Six1, and Dlx5 in cells from the J1-6d infection scheme were significantly lower than those in the cells infected with NC-shRNA, as shown by semi-quantitative RT-PCR (p < 0.01)." (PMID 34940631, 2021). "Further, the percentage of Pax8/Pax2 double-positive cells in the J1-6d infection scheme was significantly lower than that of cells infected with NC-shRNA, as shown by immunostaining with specific antibodies (Figure 2C1,C2)." (PMID 34940631, 2021). "The analyses of non-thyroid cell viabilities, however, showed that AdNKX2-1 infection did not cause HepG2 liver cell death, which does not express PAX8 or NKX2-1." (PMID 34748583, 2021).
renal disease (3 papers, 2016 to 2022). "Our study demonstrates that various kidney diseases with a chronic course that results in the formation of tubular atrophy and interstitial fibrosis lead to PAX8 expression in the nuclei of proximal tubules." (PMID 36140438, 2022). "In contrast to other organs, the involvement of PAX8 has not been widely studied in kidney diseases." (PMID 36140438, 2022).
endocrine neoplasms (1 paper, 2022). "When using older, polyclonal preparations, endocrine neoplasms (pancreatic islet cell tumors and gastrointestinal tract carcinoids) are often positive for PAX8; however, cross-reactivity with PAX6 is clarifying." (PMID 36428491, 2022).
metabolic disorders (1 paper, 2019). "However, Pax8 +/- mice did not exhibit a pro-inflammatory milieu in the liver or the skeletal muscle, which is commonly associated with metabolic disorders." (PMID 31518338, 2019).
PAX8 also shares sentences with these, for which no sentence is quoted: papillary carcinoma (6 papers); Renal neoplasm (5); uterine carcinosarcoma (4); poorly differentiated thyroid carcinoma (3); rhabdomyosarcoma (3); adenocarcinoma of the gallbladder (2); diffuse large B-cell lymphoma (2); endometrioid ovarian cancer (2); endometrioid tumor (2); gastric adenocarcinoma (2); gastric tumors (2); germ cell tumor (2); goiter (2); invasive ductal carcinomas (2); mesonephric neoplasm (2); mucinous adenocarcinoma (2); neurodegenerative disease (2); non-Hodgkin lymphoma (2); ovarian serous cystadenocarcinoma (2); renal failure (2); teratoma (2); thyroid autoimmune diseases (2); urothelial carcinoma of the urinary bladder (2); acute promyelocytic leukemia (1); alveolar soft part sarcoma (1); atherosclerosis (1); Bamforth-Lazarus syndrome (1); benign renal tumor (1); benign tumors (1); biphasic mesothelioma (1).
A further 80 diseases each share a sentence with PAX8 in 1 paper.